MAPT (microtubule associated protein tau)
Description:
Promotes microtubule assembly and stability, and might be involved in the establishment and maintenance of neuronal polarity. The C-terminus binds axonal microtubules while the N-terminus binds neural plasma membrane components, suggesting that tau functions as a linker protein between both. Axonal polarity is predetermined by TAU/MAPT localization (in the neuronal cell) in the domain of the cell body defined by the centrosome. The short isoforms allow plasticity of the cytoskeleton whereas the longer isoforms may preferentially play a role in its stabilization.
Synonyms: MAPTL; MTBT1; TAU; PPND; FTDP-17; MSTD; MTBT2; FLJ31424; MGC138549; PPP1R103; tau-40; Tau-PHF6; DDPAC; FTD1
Tractability: Small molecule: a structure with a bound ligand is known; a high-quality ligand is known; it belongs to a druggable protein family. Antibody: a drug acting on it is in phase 2 or 3 trials; UniProt places it where antibodies can reach, with high confidence; its Gene Ontology location is reachable by antibodies, with high confidence; the Human Protein Atlas places it where antibodies can reach. PROTAC: it is named in the literature on targeted protein degradation; UniProt records ubiquitination sites on it; ubiquitination databases record sites on it; its protein half-life has been measured; a small molecule that binds it is known.
Target class: Other cytosolic protein
Chemical probes: ML103, QC-01-175-1 (high quality)
Gene: Protein-coding gene on chromosome 17 (45,894,358 to 46,028,334, forward strand). Ensembl gene ENSG00000186868.
Subcellular location: Cytoplasm, cytosol; Cell membrane; Cytoplasm, cytoskeleton; Cell projection, axon; Cell projection, dendrite; Secreted
Subcellular location (Human Protein Atlas): End piece; Plasma membrane; Nuclear speckles; Predicted to be secreted
Pathways (Reactome):
Immune System: PKR-mediated signaling
Neuronal System: Activation of AMPK downstream of NMDARs
Programmed Cell Death: Caspase-mediated cleavage of cytoskeletal proteins
Gene Ontology:
Molecular function: apolipoprotein binding; enzyme binding; enzyme inhibitor activity; Hsp90 protein binding; identical protein binding; lipoprotein particle binding; microtubule binding; microtubule lateral binding; protein binding; protein kinase binding; protein-folding chaperone binding; SH3 domain binding; actin binding; DNA binding; double-stranded DNA binding; dynactin binding; histone-dependent DNA binding; microtubule stabilizing activity; minor groove of adenine-thymine-rich DNA binding; phosphatidylinositol binding; phosphatidylinositol bisphosphate binding; protein phosphatase 2A binding; protein-macromolecule adaptor activity; RNA binding; sequence-specific DNA binding; and 2 more
Biological process: amyloid fibril formation; DNA damage response; intracellular distribution of mitochondria; memory; microtubule cytoskeleton organization; negative regulation of establishment of protein localization to mitochondrion; negative regulation of gene expression; negative regulation of mitochondrial fission; negative regulation of mitochondrial membrane potential; positive regulation of axon extension; positive regulation of microtubule polymerization; positive regulation of protein localization; positive regulation of protein localization to synapse; positive regulation of superoxide anion generation; protein polymerization; regulation of autophagy; regulation of calcium-mediated signaling; regulation of cellular response to heat; regulation of microtubule cytoskeleton organization; regulation of microtubule polymerization or depolymerization; regulation of microtubule-based movement; supramolecular fiber organization; synapse organization; astrocyte activation; axon development; and 23 more
Cellular component: axolemma; axon; cell body; cytoplasm; cytoplasmic ribonucleoprotein granule; cytosol; dendrite; extracellular region; growth cone; membrane; microtubule cytoskeleton; neurofibrillary tangle; neuronal cell body; nuclear periphery; plasma membrane; somatodendritic compartment; tubulin complex; dendritic spine; glial cell projection; main axon; membrane raft; microtubule; mitochondrion; nucleus; axon cytoplasm; and 1 more
Genetic constraint (gnomAD): Loss-of-function variants: 33 observed, 61.01 expected, observed/expected ratio (o/e) 0.54, 90% interval 0.41 to 0.72. The upper end of that interval is the gene's LOEUF score, 0.72, which puts it in group 2 of 6, group 1 being the genes least tolerant of losing a copy. Missense variants: 877 observed, 1,103.5 expected, observed/expected ratio (o/e) 0.79, 90% interval 0.75 to 0.84. Synonymous variants: 451 observed, 459.1 expected, observed/expected ratio (o/e) 0.98, 90% interval 0.91 to 1.06.
Homologues: Orthologues: chimpanzee MAPT (87% identical), dog MAPT (80% identical), pig MAPT (80% identical), macaque MAPT (79% identical), rabbit MAPT (73% identical), rat Mapt (67% identical), mouse Mapt (65% identical), tropical clawed frog mapt (31% identical), zebrafish mapta (22% identical), zebrafish maptb (22% identical). Paralogues in human: MAP2 (32% identical).
Diseases named in the same sentence as MAPT in open-access papers:
MAPT is named in the same sentence as 235 diseases in open-access papers, as found by Europe PMC text mining. Sharing a sentence is not in itself a finding about the gene and the disease. The quoted sentences say what the papers report.
Alzheimer disease (627 papers, 2006 to 2026). A progressive, neurodegenerative disease characterized by loss of function and death of nerve cells in several areas of the brain leading to loss of cognitive function such as memory and language. "Accumulation of microtubule-associated protein tau is a neurotoxic hallmark in Alzheimer's disease (AD) and related tauopathies." (PMID 42054438, 2026). "The interaction between the microtubule associated protein Tau and the tyrosine kinase Fyn is believed to play a pivotal role in the early stage of Alzheimer's disease." (PMID 40322972, 2025). "Intracellular accumulation of the microtubule-associated protein TAU (MAPT) as filamentous aggregates is a hallmark of tauopathies, including Alzheimer’s disease (AD)." (PMID 41303552, 2025). "Tauopathies, including Alzheimer’s disease, are neurodegenerative disorders characterized by the accumulation of microtubule-associated protein tau, which is closely linked to cognitive decline." (PMID 41279751, 2025). "In Alzheimer’s disease (AD), the microtubule-associated protein Tau, which regulates axonal transport and synapse function, mislocalizes from axons into insoluble cytosolic inclusions called neurofibrillary tangles (NFTs)." (PMID 41107545, 2025). "Studies have shown that impaired autophagy and mitophagy are associated with the accumulation of amyloid-beta and MAPT/tau pathology, which are linked to synaptic dysfunction and memory deficits in Alzheimer disease." (PMID 40287423, 2025). "Both KANSL1 and MAPT have been linked to neurodegenerative diseases such as Alzheimer’s disease (AD), Progressive supranuclear palsy (PSP) and PD." (PMID 41394315, 2025). "Neurodegenerative diseases that involve the microtubule-associated protein tau (tau, MAPT), such as Alzheimer’s disease, corticobasal degeneration and progressive supranuclear palsy, are referred to collectively as tauopathies." (PMID 40790356, 2025). "Other mutations in MAPT have been associated with an increased risk of tauopathy, such as the A152 T variant for Alzheimer’s disease." (PMID 40349043, 2025). "Deficits in the autophagy-lysosomal pathway facilitate intracellular microtubule associated protein tau (MAPT) accumulation in Alzheimer disease (AD)." (PMID 40715737, 2025). "Tauopathies such as Alzheimer’s disease are characterized by aggregation and increased phosphorylation of the microtubule-associated protein tau." (PMID 38396035, 2024). "First, genomic analysis of genes related to Alzheimer’s disease progression shows that RAR-ligand complexes regulate the expression of microtubule-associated protein tau (MAPT) promoter gene located on chromosome 17q21 via presence of a RARE." (PMID 38572181, 2024). "A final target of NUAK1 worth mentioning for its clinical relevance in Alzheimer’s disease is TAU (encoded by MAPT), independently found by two separate groups to be stabilised upon phosphorylation of S356 by NUAK1." (PMID 38939918, 2024). "For example, the microtubule-associated protein tau, implicated in Alzheimer’s disease, has the Human Genome Organization Gene Nomenclature Committee (HGNC) gene symbol ‘MAPT’." (PMID 39056774, 2024). "For example, the gene expression of MAPT, a gene encoding Tau protein, is commonly increased in oligodendrocytes among patients with Alzheimer’s disease." (PMID 38153694, 2024). "Previous work indicates that specific protein components of these aggregates are toxic, including tau (encoded by MAPT) in Alzheimer's disease and related tauopathies." (PMID 39350752, 2024). "The microtubule-associated protein tau forms cytosolic assemblies in a number of diseases, including Alzheimer’s disease (AD) and progressive supranuclear palsy (PSP)." (PMID 39276772, 2024). "MAPT is genetically and neuropathologically associated with neurodegenerative disorders, including Alzheimer’s disease and frontotemporal dementia." (PMID 36525587, 2023).
Alzheimer disease (continued). "While more commonly associated with Alzheimer's disease, mutations in the MAPT gene, which encodes the Tau protein, have been linked to some cases of FTD." (PMID 38249293, 2023). "The microtubule-associated protein tau is known to be involved in multiple neurodegenerative diseases including Alzheimer’s disease (AD), frontotemporal dementia, progressive supernuclear palsy, and cortical basal ganglionic degeneration." (PMID 36378913, 2023). "Aberrant usage of certain alternative promoters has been associated with multiple cancers and several genes associated with Alzheimer’s disease, including the microtubule-associated protein tau gene (MAPT)." (PMID 37235648, 2023). "The microtubule-associated protein tau (MAPT) is the major constituent of the intracellular neurofibrillary tangles that are a pathological hallmark of Alzheimer’s disease (AD) and other associated tauopathies." (PMID 36724228, 2023). "Alzheimer’s disease and related tauopathies are characterized by the pathogenic misfolding and aggregation of the microtubule-associated protein tau." (PMID 36724228, 2023). "The microtubule associated protein tau is an indispensable part of the pathogenesis of Alzheimer’s disease (AD) and several related diseases called tau disease, where tau is deposited in the affected brain regions." (PMID 37396767, 2023). "The neuropathological hallmarks of Alzheimer’s disease classically include the deposition of neurofibrillary tangles and paired helical fragments comprising the microtubule associated protein tau as well as the accumulation of plaques composed of Aβ peptides." (PMID 37237961, 2023). "Overactivation of NMDA receptors in Alzheimer’s disease has been associated with the presence of the microtubule-associated protein Tau at the postsynapse." (PMID 37891164, 2023). "Tauopathy, characterized by the hyperphosphorylation and accumulation of the microtubule-associated protein tau, and the accumulation of Aβ oligomers, constitute the major pathological hallmarks of Alzheimer’s disease." (PMID 37735155, 2023). "A key histopathological hallmark of Alzheimer’s disease (AD) is the presence of neurofibrillary tangles of aggregated microtubule-associated protein tau in neurons." (PMID 36918909, 2023). "The brain accumulation of the microtubule associated protein tau (MAPT) into insoluble aggregates is a major neuropathological feature of Alzheimer’s disease (AD) and other neurodegenerative disorders referred to as tauopathies." (PMID 37553663, 2023). "Dysregulated modifications of Tau and/or mutations of MAPT underlie the pathogenesis of Tauopathy that includes Alzheimer’s disease, frontotemporal dementia, Pick’s disease, etc., making Tau a promising target for Tauopathy treatment." (PMID 37936174, 2023). "The microtubule-associated protein tau (MAPT) gene encodes the protein Tau that aggregate to form neurofibrillary tangles which are core pathological feature of Alzheimer’s disease but have also been identified in PD." (PMID 36677037, 2023). "A lot of SNPs associated with risk for Alzheimer’s disease (AD) were identified near MAPT and KANSL1 in humans, and they appeared to be correlated with an overexpression of both genes in different brain regions." (PMID 40729198, 2023). "Mutations in the MAPT gene have been linked to various neurodegenerative conditions, including Alzheimer’s disease (AD), frontotemporal dementia, cortico-basal degeneration, and progressive supranuclear palsy." (PMID 37907504, 2023). "Alzheimer’s disease (AD) is an increasingly prevalent neurodegenerative disorder whose pathological hallmarks are abnormal deposits of amyloid-beta (Aβ) and microtubule-associated protein tau (τ)." (PMID 36031051, 2023). "Hyperphosphorylation and intraneuronal aggregation of the microtubule-associated protein tau is a major pathological hallmark of Alzheimer’s disease (AD) brain." (PMID 36641439, 2023).
Alzheimer disease (continued). "The MAPT gene encodes the microtubule-associated protein tau, which has been extensively studied in Alzheimer’s disease (AD)." (PMID 37628602, 2023). "Pathological aggregation and propagation of microtubule-associated protein Tau is closely associated with Alzheimer’s disease (AD), frontotemporal dementia (FTD), and other tauopathies." (PMID 36048712, 2022). "Mutations in the genes for the amyloid-β precursor protein (APP) and the presenilins (PSEN1 and PSEN2) cause early-onset, dominantly inherited forms of Alzheimer’s disease (AD), whereas mutations in the MAPT gene mainly lead to frontotemporal dementia (FTD)." (PMID 35120450, 2022). "Alzheimer's disease (AD) is characterized by two pathological features: neurofibrillary tangles (NFTs), formed by microtubule-associated protein tau, and abnormal accumulation of amyloid-β (Aβ)." (PMID 35711910, 2022). "Alzheimer’s disease (AD) is characterized by an accumulation of oligomeric amyloid beta (Aβ) and misfolded and mislocalized microtubule-associated protein tau (MAPT; tau protein)." (PMID 35379353, 2022). "Traumatic brain injury (TBI) promotes several Alzheimer’s disease-like pathological features, including microtubule-associated protein tau (MAPT) accumulation within neurons." (PMID 36389767, 2022). "Intracellular accumulation of the microtubule-associated protein tau and its hyperphosphorylated forms is a key neuropathological feature of Alzheimer’s disease (AD)." (PMID 35527277, 2022). "This study aimed to investigate the expression levels and methylation status of microtubule‐associated protein tau (MAPT) in the blood of Alzheimer's disease (AD) patients and age‐ and sex‐matched healthy controls." (PMID 38868661, 2022). "Several neurodegenerative disorders, including Alzheimer's disease (AD), are associated with malfunction of the microtubule-associated protein Tau." (PMID 36274955, 2022). "Alzheimer’s disease (AD) is defined by intracellular neurofibrillary tangles formed by the microtubule-associated protein tau and extracellular plaques formed by the β-amyloid peptide." (PMID 35624093, 2022). "These microglia upregulate factors that have been linked to neurotoxicity, including Nox2 and pathways of Alzheimer’s Disease (AD) during the disease progression (MAPT (tau), PSEN2, and APOE genes) whose mutations are directly linked to familial AD." (PMID 36076972, 2022). "The microtubule-associated protein tau plays a central role in tauopathies such as Alzheimer’s disease (AD)." (PMID 35393558, 2022). "The presence of hyperphosphorylated microtubule-associated protein tau is strongly correlated with cognitive decline and neuroinflammation in Alzheimer’s disease and related tauopathies." (PMID 34275478, 2021). "Studies suggest that microtubule-associated protein Tau, implicated in Alzheimer’s disease, interacts with SYNGR3 causing synaptic dysfunction." (PMID 33888815, 2021). "The implication of MAPT, which is known as tau protein, is well known for its implication in Alzheimer disease, but it has also been found associated with PD." (PMID 34066091, 2021). "Genetic variation within MAPT was reported to be associated with multiple neurodegenerative disorders, including Parkinson's disease and Alzheimer's disease." (PMID 34557504, 2021). "Alzheimer’s disease (AD) is one of the tauopathies and the most common neurodegenerative disease involving the abnormal phosphorylation and accumulation of the microtubule-associated protein tau (MAPT or tau)." (PMID 34275478, 2021). "The effect of TREM2 deficiency increased after exposure of microglia to Alzheimer’s disease-associated mutated microtubule-associated protein tau (MAPT) or PSEN/APP forms indicating an altered behaviour of the mutant cells in pathological conditions." (PMID 34095831, 2021). "The microtubule-associated protein tau has a critical role in Alzheimer’s disease and other tauopathies." (PMID 33417012, 2021).